EPCAM (epithelial cell adhesion molecule)
Diseases named in the same sentence as EPCAM in open-access papers (continued):
Sharing a sentence is not in itself a finding about the gene and the disease.
endometriosis (9 papers, 2009 to 2024). The growth of functional endometrial tissue in anatomic sites outside the uterine body. "The relevance of a reduced proportion of EpCAM+ cells in EMO-OCP (two of the four participants with endometriosis) is unclear and is worthy of further investigation." (PMID 34945786, 2021). "There were several genes strongly expressed in endometriosis tissue: EPCAM, KRT18, WT1, MUC16, MUC1, and ESR1, if compared to the endometrial cells from healthy controls." (PMID 31717910, 2019). "Similar unexpected results were found for EpCAM which has also been shown to be increased in extrauterine tissues, while we saw a corresponding drop in the plasma of our endometriosis patients." (PMID 31333337, 2019). "Moreover, CECs could be isolated using the cmHsp70.1 mAb-based, and to a lesser extent EpCAM mAb-based, bead approach in all patients with endometriosis, with the highest counts obtained using the mHsp70-targeting procedure in patients with extra-uterine involvement." (PMID 39519195, 2024). "Immunoreactivity of endometriotic epithelial cells to EpCAM and N-cadherin was significantly higher compared to eutopic endometrium, which suggests that overexpression of EpCAM is engaged in Epithelial-Mesenchymal Transition (EMT) in endometriosis." (PMID 36612107, 2022). "All primary cultures derived from either control eutopic endometrium and endometriosis lesions were positive for endometrial stroma cell markers CD10 and vimentin and negative for endothelial (PECAM1) and epithelial (EPCAM) markers, indicating they represent the endometrial stromal cell compartment." (PMID 38203610, 2023).
esophageal squamous cell carcinoma (9 papers, 2006 to 2025). Esophageal squamous cell carcinoma (ESCC) is a type of esophageal carcinoma (EC) that can affect any part of the esophagus, but is usually located in the upper or middle third. "EpCAM overexpression was found in 98% and 100% cancer cells respectively in metastatic stage of esophageal squamous cell carcinoma (ESCC) and esophageal adenocarcinoma (EACA) and associated with poor prognosis in ESCC patients." (PMID 40017594, 2025). "In patients with esophageal squamous cell carcinoma, high EpCAM expression conferred a significantly higher survival rate." (PMID 37192201, 2023). "Thus, Ep-CAM testing and application of therapeutic anti-EpCAM antibodies to suitable candidates represents a chance to improve the prognosis of esophageal SCC patients." (PMID 16796747, 2006). "In esophageal squamous cell carcinoma (ESCC), epithelial cell adhesion molecule (EpCAM)-positive and cytokeratin (CK)-positive CTCs were found in 25.6% of patients." (PMID 40676582, 2025). "However, we only tested for EpCAM staining in one feline oropharyngeal squamous cell carcinoma and expression can be variable in human patients with this tumor, ranging from 62–86% of tested patients for cervical and esophageal squamous cell carcinomas, with lower expression in the former." (PMID 33614766, 2021). "EpCAM overexpression was 98% in both esophageal squamous cell carcinoma (ESCC) and esophageal adenocarcinoma (EACA) and 100% in metastasis, but no EpCAM overexpression was detected in undifferentiated EC (UEC)." (PMID 26687301, 2015).
gastric tumors (9 papers, 2013 to 2025). "To identify transcriptional changes associated with Yap1 gene ablation, we isolated EpCAM+ epithelial cells from gastric tumors obtained from 20 wk-old Gp130FF; Yap1WT and Gp130FF; Yap1KO mice for bulk RNASeq analysis." (PMID 37957015, 2024). "EPCAM was over-expressed in 27 gastric tumor tissue samples compared with matched normal gastric mucosa." (PMID 24422715, 2013). "In 42 gastric tumor tissue samples and matched normal gastric mucosa, the average expressions of EPCAM were 0.4199 ± 0.0485 and 0.1759 ± 0.0144, respectively, and were significantly different (t = 3.122, P = 0.002)." (PMID 24422715, 2013). "Similarly, EpCAM, a widespread marker on epithelial carcinomas, and MUC1, a glycoprotein aberrantly glycosylated in gastric tumors, serve as attractive targets for next-generation CAR-T constructs." (PMID 41614808, 2025). "EpCAM and CLDN18.2 are only co-expressed in stomach tumor, but not in other tumors." (PMID 40057807, 2025).
metastatic prostate carcinoma (9 papers, 2012 to 2024). A carcinoma that arises from the prostate gland and has spread to other anatomic sites. "In summary, this study revealed that EpCAM antibodies were more effective in isolating CTCs from patients with localized prostate cancer, while vimentin antibodies were superior for in metastatic prostate cancer." (PMID 37345161, 2023). "CELLSEARCHTM was the first and only FDA-approved assay to date for CTC quantitation by enriching for EpCAM-positive cells in the monitoring of patients with advanced breast, colorectal, and metastatic prostate cancer." (PMID 34771462, 2021). "As a result, we show that the device can efficiently capture CTCs from patients with localized and metastatic prostate cancer through anti-EpCAM, anti-PSA, and anti-PSMA antibodies, and it is suitable for AFM measurements of captured intact CTCs." (PMID 34567635, 2020). "For us it was a concern that we detected ≥5 CTCs (EpCAM+/CK+/CD45-) in only two out of 10 analyzed blood samples from metastatic prostate cancer patients." (PMID 32021935, 2020). "Based on the classification of being EpCAM+/CK+/CD45-we detected ≥5 CTCs in two out of 10 analyzed blood samples from patients with metastatic prostate cancer." (PMID 32021935, 2020). "Interestingly, EpCAM antibodies were more effective for localized prostate cancer, while vimentin antibodies excelled in metastatic prostate cancer isolation." (PMID 37345161, 2023). "To check if the isolated fractions represent tumoral subpopulations with differential phenotypes we performed gene expression analysis by RT-qPCR of CTCs isolated from patients with prostate metastatic cancer (n = 8; 26 ± 19.79 x 106 PBMCs) using anti-EpCAM, anti-EGFR and anti-FGFR magnetic beads." (PMID 27711186, 2016). "Adding TRA-1-60 expression (TRA+) to the analysis (EpCAM+/CK+/CD45-/TRA+) we were only able to identify one patient with metastatic prostate cancer (out of 10) by detection of ≥5 CTCs (data not shown)." (PMID 32021935, 2020). "However, because CTCs expressing low EpCAM levels are frequently missed using CellSearch®, it is likely that anti-PSMA capture maybe be a more consistent methodology for CTC isolation in metastatic prostate cancer patients." (PMID 22558290, 2012).
acute lymphoblastic leukemia (8 papers, 2018 to 2023). Leukemia with an acute onset, characterized by the presence of lymphoblasts in the bone marrow and the peripheral blood. "The current preliminary study was designed to measure the mRNA expression of EpCAM, a cell proliferation gene, in acute lymphoblastic leukemia." (PMID 36428553, 2022). "In the current research study, qPCR induced expression of EpCAM was noted in acute lymphoblastic leukemia (ALL) cases." (PMID 36428553, 2022). "Two bispecific antibodies have already been approved, Catumaxomab and Blinatumomab, targeting EpCAM and CD3 and CD19 and CD3 in malignant ascites and acute lymphoblastic leukemia, respectively." (PMID 37767396, 2023). "Catumaxomab, a rat-mouse hybrid targeting epithelial cell adhesion molecule (EpCAM) and CD3, and blinatumomab, a mouse antibody targeting CD19 and CD3, have been approved by the FDA for treating malignant ascites and acute lymphoblastic leukemia, respectively." (PMID 29335534, 2018). "Effective therapies include catumaxomab for EpCam-positive gastric and ovarian cancer and blinatumomab for CD19-positive acute lymphoblastic leukemia (ALL)." (PMID 29685160, 2018).
acute myeloid leukemia (8 papers, 2021 to 2026). Acute myeloid leukemia (AML) is a group of neoplasms arising from precursor cells committed to the myeloid cell-line differentiation. "WNT5B was also shown to be highly expressed in EpCAM+ cells (leukemia stem cells) in acute myeloid leukemia (AML) and to associate with the resistance of EpCAMhigh myeloid leukemia cells to cytotoxic chemotherapy." (PMID 34017835, 2021). "Moreover, rapamycin pretreatments can attenuate mTORC1 activity and upregulate CXCR4, which promotes the migration and penetration abilities of EpCAM CAR T cell for eliminating acute myeloid leukemia (AML) in bone marrow." (PMID 36369033, 2022). "In the preclinical studies, BiKE has been effectively used to target CD19/CD22 on B cell non-Hodgkin's lymphoma, CD33 on acute myeloid leukemia (AML) and myelodysplastic syndromes (MDS), EpCAM on various carcinomas, and CD133 on cancer stem cells." (PMID 39415291, 2024). "Epithelial cell adhesion molecule (EpCam), alternatively named epithelial specific antigen (ESA), has been found in various epithelial tumours as well as in acute myeloid leukemia." (PMID 37108193, 2023). "EpCAM+ acute myeloid leukemia (AML) displays enhanced tumorigenicity and chemoresistance compared to EpCAM− AML cells." (PMID 36369033, 2022).
acute pancreatitis (8 papers, 2007 to 2025). An acute inflammatory process that leads to necrosis of the pancreatic parenchyma. "The issue with these were that, rather than sparing normal epithelial cells that have both a low target expression and an almost hidden expression due to EpCAM only being present on the basolateral membrane, they bound to all cells expressing EpCAM and caused acute pancreatitis." (PMID 29329202, 2018). "Systemic intolerability of an EpCAM-specific immunotoxin and trispecific antibodies, and acute pancreatitis, as seen with high-affinity EpCAM mAbs appears consistent with a collateral damage of normal EpCAM-expressing tissue." (PMID 17211480, 2007). "For instance, high-affinity EpCAM-specific mAbs were shown to cause severe acute pancreatitis, whereas low-affinity counterparts lacked sufficient effector functions." (PMID 23134699, 2012). "However, acute pancreatitis may be a concern with regard to high-affinity EpCAM mAbs, such as heING1." (PMID 40358156, 2025). "According to clinical reports, both the high-affinity anti-EpCAM antibodies, ING-1 and 3622W94, cause acute pancreatitis, while the other low-affinity anti-EpCAM antibodies, adecatumumab and edrecolomab, produced neither pancreatic side-effects nor any anti-tumor effects." (PMID 30140380, 2018). "From the present in-vitro data, the induction of acute pancreatitis by mAbs 3622W94 and ING-1 is best explained by their high binding affinities for EpCAM seen in Biacore analyses, in particular their very slow off-rates." (PMID 21044305, 2010). "Both had a relatively high binding affinity for EpCAM, had a maximum tolerated dose (MTD) of 1 mg/kg bodyweight, and their dose-limiting toxicity was acute pancreatitis." (PMID 21044305, 2010). "A moderate binding affinity and recognition of a distinct domain of EpCAM may best explain why adecatumumab showed a larger therapeutic window in cancer patients than the two high-affinity IgG1 antibodies ING-1 and 3622W94, both of which caused acute pancreatitis." (PMID 21044305, 2010).
COVID-19 (8 papers, 2020 to 2023). A disease caused by infection with severe acute respiratory syndrome coronavirus 2. "Although the epithelial cells from the COVID-19 patients with either severe or mild symptoms exhibited a similar level of EPCAM gene expression, the hub gene expression was clearly altered between the two groups of patients." (PMID 34497809, 2021). "Similarly, the epithelial cell adhesion molecule CD326 (EpCAM) was significantly higher (P<0.01) in EPs derived from COVID-19 patients than in controls." (PMID 37207201, 2023). "The presence of CASP3, EPCAM, KRT19, and TGFA in the red module therefore suggests that one of the key features of the post-COVID-19 airway is the presence of ongoing epithelial injury and repair." (PMID 35151371, 2022). "Additionally, a smaller number of biopsies (COVID-19 n = 5, controls n = 6) were analyzed for the expression of ACE2 and TMPRSS2 as mediators of virus entry as well as for the expression of EpCAM, CD8α, CD31, and CD163." (PMID 34420043, 2021). "In COVID-19 the homeostatic equilibrium between TREG cells (IL-10) and Th17 cells (IL-17) is broken: inflammatory cytokine levels (IL-1, TNF) are elevated in the lungs of COVID-19 patients, resulting in an increase in HA-synthase-2 (HAS2) in alveolar epithelial cells CD31+, EpCAM+ and fibroblasts." (PMID 33160363, 2020).
liver cirrhosis (8 papers, 2014 to 2023). "Being peritumoral EpCAM positive was also significantly associated with larger tumor size, liver cirrhosis, and more frequent vascular invasion." (PMID 28572700, 2017). "In a trial of 25 subjects and 25 controls with decompensated liver cirrhosis due to various causes, subjects received fetal liver-derived EpCAM+ cell infusions into the liver via the hepatic artery and showed improvement in multiple diagnostic and biochemical parameters." (PMID 26880956, 2016). "Compared with a normal liver, a significantly higher expression of “stemness genes” has been found in liver cirrhosis and EpCAM-positive HCC." (PMID 36674932, 2023). "On the other hand, patients with liver cirrhosis who were infused with EpCAM-positive stem cells showed a significant decrease in MELD score and a marked clinical improvement." (PMID 35070966, 2021). "Being EpCAM positive tended to correlate with a larger tumor size (p = 0.040), liver cirrhosis (p = 0.023), and more frequent vascular invasion (p = 0.002)." (PMID 28572700, 2017). "This suggests that EpCAM-positive liver CSCs may appear both in liver cirrhosis and during the formation of HCC." (PMID 36674932, 2023). "In the etiology of liver cirrhosis and HCC, CD133/EpCAM-expressing cells emerged due to either chronic HCV or HBV infection." (PMID 37880659, 2023). "In addition, the upregulation of EpCAM expression due to regenerative activity during inflammatory reactions which raises the possibility that upregulation of EpCAM expression in HCC may be partially due to the inflammatory response accompanying the underlying cause of HCC as liver cirrhosis." (PMID 32212818, 2020). "EpCAM- sorted cells from fetal livers have been used already in clinical trials of cell therapy of advanced liver cirrhosis without the need of immune-suppressants." (PMID 25471120, 2014).
liver disease (8 papers, 2015 to 2025). "A flow cytometry analysis showed that the positivity rate of EpCAM was higher in the healthy group than in the liver disease group, and the positivity rate of TROP2 was higher in the liver disease group." (PMID 39636897, 2024). "Overall, the genetic evidence of EpCAM+Gli1+ cells in liver repair provides new insights into the cellular and molecular mechanisms of liver disease and regeneration." (PMID 36316325, 2022). "De novo expression of EpCAM has been reported in mature human hepatocytes during various inflammatory liver diseases and liver regeneration and repair." (PMID 33333805, 2020). "As previously seen with both FGF19 and FGFR4, EpCAM expression also appeared to increase with the histological severity of inflammation and liver disease, demonstrating a significant positive correlation between EpCAM expression and histopathologic changes from ST to HCC (r = 0.947)." (PMID 27447573, 2016). "Using flow cytometry, the EpCAM positivity rate was higher in the healthy group and the TROP2 positivity rate was higher in the liver disease group." (PMID 39636897, 2024). "The research established that circulating EpCAM-positive cells are seldom seen in non-malignant liver disorders and that their presence generally signifies a malignant etiology." (PMID 40426850, 2025). "EPCAM+ status, in combination with annexin V+ and ASGPR1+ fluorescence labeling, can be used as a noninvasive assessment of the presence and extent of CCA in patients with advanced liver diseases." (PMID 36300097, 2022). "Our findings confirm the limited existing data suggesting that circulating EpCAM-positive epithelial cells are rare in patients with non-malignant liver diseases, and that EpCAM-positive cells in HCC patients are generally of tumor origin." (PMID 25884197, 2015).
neuroendocrine tumors (8 papers, 2010 to 2025). "That EpCAM positivity was more common in several neuroendocrine neoplasms than CKpan positivity fits well with the particularly high EpCAM expression in normal neuroendocrine cells in the gastrointestinal tract." (PMID 38786342, 2024). "The rate of TROP2 positivity was markedly lower than for EpCAM in testicular germ cell tumors, neuroendocrine neoplasms, renal cell tumors, and also in many gastrointestinal adenocarcinomas." (PMID 38786342, 2024). "Among 78 epithelial tumor types, the EpCAM positivity rate was ≥90% in 60 categories—including adenocarcinomas, neuroendocrine neoplasms, and germ cell tumors." (PMID 38786342, 2024). "In comparison to CKpan and TROP2 antibodies, EpCAM staining is particularly common in seminomas and in neuroendocrine neoplasms." (PMID 38786342, 2024). "The positivity rate was higher for EpCAM (100%) than for CKpan (23.2%; p < 0.0001) in testicular seminomas and—less markedly—in several neuroendocrine neoplasms." (PMID 38786342, 2024). "Additionally, we observed significant EpCAM-targeted fluorescence in positive LNs from different primary tumor histologies, including adenocarcinoma and neuroendocrine tumors." (PMID 41087662, 2025). "Thus, primary tumor histology was analyzed to determine correlation with EpCAM-targeted fluorescence of positive LNs including primary adenocarcinoma tumors (n = 42) and primary neuroendocrine tumors (n = 6)." (PMID 41087662, 2025). "However, CTCs may be missed when epithelial markers, such as EpCAM, are downregulated in the tumor tissue, as was shown in neuroendocrine tumors of the lung." (PMID 31412616, 2019).
osteosarcoma (8 papers, 2012 to 2025). A usually aggressive malignant bone-forming mesenchymal neoplasm, predominantly affecting adolescents and young adults. "SJSA-1 osteosarcoma cell line was used, which is expected to be low on epithelial cell adhesion molecule (EpCAM) expression (the main target for affinity-based CTC capture), and it is a good candidate for size-based capture." (PMID 38675332, 2024). "In Han’s study, Raman bands at 1000, 1075, and 1375 cm−1 (CD63, vimentin (VIM), and epithelial cell adhesion molecule (EpCAM)) in exosomes of osteosarcoma patients were significantly higher." (PMID 36814817, 2023). "Over-expression of EpCAM was recently observed in all osteosarcomas, half of the angiosarcomas and 62.5% of the leiomyosarcomas, indicating the broad spectrum of tumours that might be targeted." (PMID 27842504, 2016). "We also used U2OS osteosarcoma and the EpCAM-negative HeLa endometrial epithelial cell line, which display an absence of EpCAM similar to Caco2 EPCAM-KD cells 78,79." (PMID 33850145, 2021).
cyst (7 papers, 2015 to 2025). A sac-like closed membranous structure that may be empty or contain fluid or amorphous material. "Under such conditions, classical cyst organization was disrupted in EpCAM-silenced cells, with increased amounts of multi-layered, unshaped and/or multilumenal cysts." (PMID 28084299, 2017). "In addition, we isolated duct‐like cell‐fibroblast clusters from 4‐week‐old KC mice using mechanical dissociation and Fluorescence‐Activated Cell Sorting (FACS) with anti‐EpCAM/PDGFRα antibodies for cyst formation analysis and 3D spheroid assay." (PMID 37964407, 2023).